KYAT1 (kynurenine aminotransferase 1 )
Gene: Protein-coding gene on chromosome 9 (128,819,663 to 128,881,931, reverse strand). Ensembl gene ENSG00000286112.
Genetic constraint (gnomAD): Loss-of-function variants: 58 observed, 63.93 expected, observed/expected ratio (o/e) 0.91, 90% interval 0.73 to 1.13. Missense variants: 575 observed, 700.72 expected, observed/expected ratio (o/e) 0.82, 90% interval 0.76 to 0.88. Synonymous variants: 239 observed, 261.16 expected, observed/expected ratio (o/e) 0.92, 90% interval 0.82 to 1.02.
Diseases named in the same sentence as KYAT1 in open-access papers:
KYAT1 is named in the same sentence as 16 diseases in open-access papers, as found by Europe PMC text mining. Sharing a sentence is not in itself a finding about the gene and the disease. The quoted sentences say what the papers report.
depression (2 papers, 2021 to 2024). "The results indicated that Atp6v1f, Arpc5, Adcyap1r1, Ndufb6, and Psmc6 were distinctly dysregulated in the hypothalamus of the depression-susceptible group, while Gys1, Pgp, Klc1, Chka, Ncstn, Ndufa6, and Kyat1 were distinctly dysregulated in the anxiety-susceptible group." (PMID 33737865, 2021).
hepatocellular carcinoma (2 papers, 2021 to 2026). A malignant tumor that arises from hepatocytes. "Our previous work has demonstrated the utility of mRNA-based KYAT1 delivery in hepatocellular carcinoma models." (PMID 41412036, 2026).
liver cancer (2 papers, 2023 to 2026). An epithelial or non-epithelial malignant neoplasm that arises from the liver. "This study demonstrates that structure-guided mutagenesis of human KYAT1 significantly alters its catalytic profile toward MSC, enhancing its therapeutic potential in liver cancer cells, and possibly other cancer models." (PMID 41412036, 2026).
Anxiety (1 paper, 2021). Intense feelings of nervousness, tension, or panic often arise in response to interpersonal stresses. "It was observed that the expressions of Gys1, Chka, Ncstn, and Ndufa6 were significantly down-regulated whereas Pgp, Klc1, and Kyat1 were up-regulated in the anxiety-susceptible group as compared to the control group." (PMID 33737865, 2021).
COVID-19 (1 paper, 2022). A disease caused by infection with severe acute respiratory syndrome coronavirus 2. "In random forest models for COVID-19, CST5, DPP7, NADK, KYAT1 and TYMP showed the highest variable importance." (PMID 35967328, 2022).
ischemic stroke (1 paper, 2021). A stroke disorder caused by obstruction of blood flow to the brain, due to thrombotic (local blood clot formation) or embolic (due to a blood clot or other material traveling from another site) event. "We present data demonstrating associations between ischemic stroke and variants of four genes (TPH1, IDO1, KYAT1 and AADAT) encoding enzymes of Trp metabolism." (PMID 34680558, 2021). "Furthermore, we also wished to learn whether changes are detectable in the expression of TPH1, TPH2, IDO1, KYAT1 and AADAT genes in peripheral blood samples (PBS) of ischemic stroke patients during the course of the disease." (PMID 34680558, 2021).
schizophrenia (1 paper, 2016). A major psychotic disorder characterized by abnormalities in the perception or expression of reality. "Kynurenine aminotransferase 1 is known to be involved in tryptophan metabolism (DBGET: T01001, hsa00380), where it converts kynurenine, an intermediate of the tryptophan degradation pathway, into kynurenic acid, a neurotoxic compound associated with schizophrenia." (PMID 27884205, 2016).
steatosis (1 paper, 2024). Increased lipid within the cytoplasm of cells. "Individuals with PWS and steatosis revealed elevated levels of the KYAT1 gene compared with those without the condition." (PMID 39336733, 2024).
Stroke (1 paper, 2021). Sudden impairment of blood flow to a part of the brain due to occlusion or rupture of an artery to the brain. "Furthermore, we examined the mRNA levels of TPH1, IDO1 and KYAT1 genes in peripheral venous blood with the aim of assessing (i) whether there are changes in their expression during the course of stroke and (ii) does any of their investigated SNPs have an impact on gene expression." (PMID 34680558, 2021).
cancer (4 papers, 2021 to 2026). A tumor composed of atypical neoplastic, often pleomorphic cells that invade other tissues. "MicroRNA-guided tumor-specific induction of KYAT1 combined with the MSC has great potential in treating cancers beyond cure." (PMID 37342563, 2023). "MicroRNA-guided tumor-specific induction of KYAT1 in combination with the non-toxic prodrug (MSC) has a great potential in the treatment of cancers that are currently beyond cure such as HCC." (PMID 34356326, 2021).
tumor (4 papers, 2020 to 2023). "KYAT1 expression was significantly reduced in cells with high levels of miR122 supporting the concept of miR-guided induction of tumor-specific cytotoxicity." (PMID 34356326, 2021). "We present herein a novel strategy to achieve efficient and specific tumoricidal effects by combining the prodrug MSC with tumor-specific microRNA-guided overexpression of KYAT1." (PMID 34356326, 2021). "Hence, the selective induction of KYAT1 in tumor cells in the presence of MSC may represent an attractive route to selectively induce cytotoxicity in tumor cells." (PMID 34356326, 2021). "Thus, the β-elimination activity of KYAT1 could be a valuable biomarker for determining which tumor would respond to MSC treatment." (PMID 32033380, 2020). "Several publications have shown the anti-tumor and chemo-preventive effects of MSC metabolites produced by KYAT1, metabolites such as methylselenol and β-methylselenopyruvate (MSP)." (PMID 32033380, 2020). "Both metabolites of MSC by KYAT1, i.e., MS and MSP, possess anti-tumor and anti-proliferative properties." (PMID 32033380, 2020).
cardiovascular diseases (1 paper, 2022). "On the contrary, FAM72A, KYAT1, LRRC38, and PTCHD4 had little or no known associations with cardiovascular diseases so far although they are moderately expressed in the heart and may have unidentified functions in AF." (PMID 36078037, 2022).
KYAT1 also shares sentences with these, for which no sentence is quoted: allergic asthma (1 paper); kidney failure (1); liver diseases (1); liver steatosis (1).